FOXP3 (forkhead box P3)
Diseases named in the same sentence as FOXP3 in open-access papers (continued):
Sharing a sentence is not in itself a finding about the gene and the disease.
tumor (continued). "In this regard, it is interesting to note that CD39+ tumor-infiltrating Treg in our patient cohort express more Foxp3 on a per cell basis than CD39− Treg, suggestive of a more immunosuppressive effector Treg subset associated with poor patient outcome." (PMID 30651930, 2018). "This was particularly evident in the RENCA model, which clearly shows decreases in all lymphocyte populations (CD8 T cells, Tregs, CD4+Foxp3-, B cells, and NK cells) with tumor progression." (PMID 30388137, 2018). "The in vivo study of HNSCC mouse model showed that the A2AR antagonist, SCH58261, not only delayed the tumor growth but also significantly reduced the population of CD4+ Foxp3+ Tregs and increased the anti-tumor response of CD8+ T cells in HNSCC tumors." (PMID 30061885, 2018). "In ESCC microenvironment, significant low Foxp3+, CD4+ and CD8+ T cells were observed to correlate with improved survival of the cancer, and high tumor-infiltrating neutrophil was significantly associated with progression of the disease." (PMID 30305803, 2018). "Here, we show for the first time that a low level of tumour cell E-cadherin is associated with low levels of immune cells (CD8+ T cells, CD68+ macrophages or FoxP3+ T-regs) in the tumour nest." (PMID 29416729, 2018). "It is thus instrumental to look further into the potential function of TZD drugs on Foxp3+ Treg cells in tumor models as suggested by current study." (PMID 30400642, 2018). "Nevertheless, the balance between pro-inflammatory CD8+ tumor-infiltrating immune cell subpopulations and Foxp3+ T cells, and their impact at different disease stages on GBC patient survival has not yet been established." (PMID 29499656, 2018). "Our study found significant hypomethylation of FOXP3-TSDR in tumor-infiltrating CD4+ T cells of CRC patients, which is consistent with the results of other investigators." (PMID 30013992, 2018). "In the study, a positive association was found between high membrane and total CCR7 expression, and the presence of FOXP3+ tumor infiltrating cells in the adjacent stroma, as well as a trend for higher intratumoral FOXP3+ cells." (PMID 30213113, 2018). "A low % of FOXP3+ T cells (and high % of CD8+ T cells) in para-cortical (tumour-free) areas of metastatic ALNs was significantly associated with ALN pCRs." (PMID 29390966, 2018). "We have shown that Ad-RTS-mIL-12+veledimex elicited a dose-related increase in tumor IL-12 which in turn elicited a dose-related increase in CD3+CD8+cytotoxic T cells concomitant with a reduction in FOXP3+ regulatory T cells." (PMID 29755109, 2018). "Using immunohistochemical analysis, we counted the numbers of CD4+, CD8+, and Foxp3+ T lymphocytes both in the invasive front and tumor bulk." (PMID 29732001, 2018). "We observed that NAC treatment increased the percentage of tumor-infiltrating wild-type CD45.2+ Foxp3– T cells, enhanced the expression of IFN-γ in tumor-infiltrating wild-type Treg cells and promoted the tumor infiltration of CD8+ effector T cells." (PMID 30089837, 2018). "The patients with a high percentage of Foxp3+ T cells in the tumor (≥ 17.98%) had a lower RFS rate than did those with a low percentage of Foxp3+ T cells (< 17.98%)." (PMID 30261082, 2018). "The presence of CD3+, CD4+, CD8+, and forkhead box protein P3-positive (FOXP3+) TILs in tumor tissues obtained from 93 patients during surgery was examined using immunohistochemistry." (PMID 30153850, 2018). "The prognostic impact of intra-tumor FoxP3+ Tregs and CD8+ TILs on OS was analyzed by univariate and multivariate analyses." (PMID 30359281, 2018). "A smaller number of CD68+ macrophages and FoxP3+ T–regs were observed with roughly equal distributions between tumour nest and stroma." (PMID 29416729, 2018). "In this study, B-9-3 in both standard and tumor-bearing mice reduced the number of CD4+CD25+FOXP3+ regulatory T cells in both the blood and in the spleen." (PMID 30079021, 2018).
tumor (continued). "CD3, CD8, and FOXP3 mRNA expressions were also measured in 90 available lymph node samples that were paired to the primary tumor samples." (PMID 30240146, 2018). "Tumor tissues from 80 GBC patients were analyzed by immunohistochemistry for the presence of CD3+, CD4+, CD8+, and Foxp3+ T cell populations, and the results were associated with clinical stage and patient survival." (PMID 29499656, 2018). "PD-1 expression was present in infiltrating immune cells, and CD3+, CD8+, and FOXP3+ T cell infiltration in tumor tissues was evident." (PMID 30003113, 2018). "They showed that there was a statistically significant difference in the ratio of CD8 T-cells to FOXP3 T-regulatory cells (CD8/FOXP3) detected in tumor cells following SBRT as compared to conventionally fractionated therapy." (PMID 29301352, 2018). "The CTLA-4 antibody mediates anti-tumour immunity through Akt phosphorylation and the blockade of Foxp3+ Treg cells in the TME, which allows for potent T-cell expansion." (PMID 29848327, 2018). "Blood and tumour-infiltrating Tregs (FOXP3+, CTLA-4+, PD-1+) play a crucial role in controlling the anti-cancer cellular immune responses in the circulation and tumour microenvironment." (PMID 29390966, 2018). "Tumor-infiltrating Tregs are featured in the enhancement of accumulation of forkhead box P3 (Foxp3) together with inhibitory molecules such as PD-1, CTLA-4, LAG-3, and TIM-3 during tumor progression." (PMID 30603054, 2018). "In our studies, the expression of Foxp3 was found to be elevated (up to 8-fold) in splenocytes from mice treated with calcitriol and its analogs, but only during the early stage of tumor growth (day 21)." (PMID 30037009, 2018). "As a transcription factor, FOXP3 can exert its tumor-suppressive activities in the nucleus, by regulating a network of oncogenes involved in various cellular functions." (PMID 29549328, 2018). "In Tregs derived from human cervical cancer tumor tissues, ERα blockade abolished FoxP3 expression and impaired suppressive function." (PMID 30337927, 2018). "It has been reported that NRP1 mediates the infiltration of the Foxp3+ Treg cell into the tumor and regulates the immunological anti-tumor control in response to tumor-derived VEGF." (PMID 30532711, 2018). "Peripheral induction of Tregs was further confirmed by transfer of FACS sorted FOXP3-GFPNeg Marilyn cells into tumor-bearing mice." (PMID 29844317, 2018). "Compared to the Senp3+/+Foxp3-Cre mice, the Senp3fl/flFoxp3-Cre mice displayed a profound reduction in tumor size and in the frequency of tumor-infiltrating Treg cells." (PMID 30089837, 2018). "Our study improved the mechanism of FOXP3-TSDR hypomethylation in tumor-infiltrating CD4+ T cells of CRC patients." (PMID 30013992, 2018). "CD8+ and CD141+ cells, PD-L1+ tumor cells, and Foxp3 T regulatory cells were preferentially induced by R-115, along with a decrease in the number of intratumoral CD11b+ cells." (PMID 30080893, 2018). "The ratios of CD3+CD8+ cytotoxic T cells, CD49b+NK cells, CD4+CD25+FoxP3+ Tregs and Gr1+CD11b+ MDSCs in tumor-DLN or spleen were examined by flow cytometry." (PMID 29301578, 2018). "A similar trend was observed for CD3, FOXP3, PD-L1 and PD-1 when were compared tumor samples from patients with stable and progressive disease." (PMID 30546030, 2018). "The significant infiltration of FOXP3-expressing T cells to the tumor mass suggest a regulatory role for this these immune cells in Oncopig tumors." (PMID 29930558, 2018). "By breeding APCmin/+ mice with DEREG mice, which harbour a high affinity diphtheria toxin receptor under the control of the FOXP3 promoter, we were able to deplete Treg in tumor-bearing mice." (PMID 29671006, 2018). "To confirm the effect of B-9-3 on Treg population, we performed immunohistochemistry analysis of tumor tissue and spleen using a monoclonal antibody against Foxp3." (PMID 30079021, 2018).
tumor (continued). "Other immune cells, such as CD4+ helper T cells or FOXP3+ regulatory T cells, or even tumor cells themselves stimulate or suppress the immune response." (PMID 30619761, 2018). "Using flow cytometric analysis, we found that the number of CD11b+Gr-1hi MDSCs and CD4+CD25+Foxp3+ Treg cells within the tumor microenvironment was remarkably reduced in CQ-treated tumor-bearing mice, compared with those in the control group." (PMID 29491374, 2018). "CCL1, but surprisingly not CCL22, showed a significant correlation with the number of tumor-infiltrating FoxP3+ Treg (p< 0.001)." (PMID 30572845, 2018). "The tumor infiltrates CD4+ T cells that expressed the transcription factor of FOXP3 (FOXP3), which acts on the regulatory T (Treg) cells that impeded the effective immune response to cancer cells, show significantly worse prognosis." (PMID 29658188, 2018). "Compendiously, the crosstalk between hyperactive Notch3 and canonical NF-κB pathways upregulates Foxp3 expression, thus enhancing the suppressive function of Tregs against protective antitumor immune responses in tumor microenvironments." (PMID 30364244, 2018). "With regard to Tregs, the FOXP3 signature locus was significantly demethylated in CD4+ T cells from the tumour compared to PBMCs (p < 0.001)." (PMID 30075815, 2018). "In intraperitoneal papillary epithelial ovarian cancer, CXCR4 antagonism increased tumor cell apoptosis and necrosis, reduced intraperitoneal dissemination, and selectively reduced intratumoral FoxP3 Tregs." (PMID 30622535, 2018). "Significantly higher density of CD8+ cells (median 402.56 vs. 121.32; Z = − 10.0411, p < 0.0001) and Foxp3+ T cells (median 113.53 vs. 28.49; Z = − 10.0969, p < 0.0001) were found in the surrounding tissues than those within the tumor nests." (PMID 30474571, 2018). "Our study also adds a new layer of information to the previous understanding of how FOXP3 functions in Treg development and acts as a tumor suppressor in cancer development." (PMID 30011797, 2018). "Foxp3 is known as the most specific marker distinguishing Treg cells from T cells, and in our study Foxp3 was expressed on tumor-infiltrating lymphocytes - tumor cells were entirely negative." (PMID 28669079, 2018). "A clear example of this FoxP3-mediated GARP expression is the conversion of tumor-specific Th17 cells to ex-Th17 FoxP3+ cells that show upregulation of surface GARP as a transdifferentiation-associated marker." (PMID 29458436, 2018). "A panel of eight different markers was developed, including CD3, CD8, CD45RO, CD68, PD-1, PD-L1, FoxP3, as well as pan- cytokeratin and Sox10 as tumor markers." (PMID 30400835, 2018). "The P60 compound is a peptide able to inhibit FOXP3 function, impeding the transcription of FOXP3 target genes that has been proven to enhance the efficacy of anti-tumor vaccines." (PMID 30340426, 2018). "Fifteen days after tumor challenge, the frequency of Foxp3-GFP+ cells in the tumor draining lymph node (TDLN) and spleen of treated and untreated animals was analyzed by fluorescence-activated cell sorting (FACS)." (PMID 29899823, 2018). "In line with the higher density of Foxp3 on the CD39+ Treg population in the tumor, our data indicate that CD39+ Treg more frequently belong to the CD4+CD45RA−Foxp3hi activated Treg population, compared to CD39− Treg." (PMID 30651930, 2018). "To investigate the mechanisms by which the tumor-suppressive function of FOXP3 is inhibited, we focused on the interaction of FOXP3 with other proteins." (PMID 29549328, 2018). "A high % CD8+ and low % FOXP3+ T cells and high CD8+: FOXP3+ ratio in metastatic ALNs (tumour-free para-cortex) were associated with pCRs." (PMID 29390966, 2018). "More recently FOXP3 has emerged as a tumour suppressor in breast and prostate epithelia, repressing a number of oncogenes including c-myc, Ezh2, HER-2/ErbB2 SKP2 and SATB1, while up regulating expression of tumour suppressors p21 and LATS2." (PMID 29963231, 2018).
tumor (continued). "On the other hand, the number of suppressor T cells (FoxP3+) was higher in the tumor beds of A9+vector as compared to A9+IL-33." (PMID 30205617, 2018). "Chemokine expression and tumor infiltration by regulatory T cells, determined by expression of the transcription factor FoxP3, were quantified and their correlation to clinical features was statistically analyzed." (PMID 30572845, 2018). "Overexpression of FOXP3 contributed to cell apoptosis as well as suppressed tumor cells’ proliferation." (PMID 30378283, 2018). "FOXP3 promotes tumor proliferation in melanoma, thyroid cancer cells and radiation-induced T-cell leukemia in Balb/c mice." (PMID 30103821, 2018). "Comparison between metastatic ALNs with a pCR and without a pCR following NAC demonstrates a significantly high level of CD8+ T cells (p = 0.048) and low level of FOXP3+ T cells (p = 0.019) in the para-cortical compartment (tumour-free) of the ALNs." (PMID 29390966, 2018). "The number of CD8+ TILs and FOXP3+ TILs in biopsy specimens and residual tumours was evaluated by immunohistochemistry." (PMID 30233820, 2018). "Another protein is Foxp3+, its higher expression in tumor cells predicts good outcome but in Tregs the function is inverse." (PMID 29682534, 2018). "It has been shown that Gr-1+CD115+ MDSCs can promote the development of Foxp3+ Tregs in vivo and mediate the inactivation of tumor-specific T cells in a tumor mouse model." (PMID 30670926, 2018). "By breeding APCmin/+ mice with depletion of regulatory T cell (DEREG) mice, which harbour a high affinity diphtheria toxin (DT) receptor under the control of the FOXP3 promoter, we were able to deplete Treg by DT injections in tumor-bearing mice." (PMID 29671006, 2018). "FOXP3 has been reported to regulate the expression of various genes involved in carcinogenesis to exert its tumor suppressor function." (PMID 29970908, 2018). "We investigated impact of treatment on proliferation and apoptosis of effector CD8+ T cells and immunosuppressive CD4+Foxp3+ Tregs, as well as effector cytokines and chemokines in tumor and peripheral tissues." (PMID 30400822, 2018). "Removal of Foxp3+ Tregs can evoke and enhance the anti-tumour immune response because they not only suppress aberrant immune responses but also inhibit anti-tumour immune responses." (PMID 29848327, 2018). "A meta-analysis including 17 types of cancer showed that the prognostic effect of Foxp3+ Tregs varied greatly according to tumor site." (PMID 30285868, 2018). "Compared with a-CTLA-4, treatment of tumor-bearing mice with a-CTLA4-TGFβRII resulted in a marked decline of FOXP3-expression in CD4+ cells." (PMID 29467463, 2018). "We then investigated the intratumoral infiltration of regulatory T cells (Tregs, CD3+CD4+CD25+Foxp3+) was examined by flow cytometric examination since Tregs are capable of restraining effective anti-tumor immune responses of CTLs42." (PMID 29670088, 2018). "c and fraction of tumor border CD8 T cells positive for granzyme B (Gzm B) and tumor border CD4 T cells positive for Foxp3." (PMID 30285905, 2018). "The presence of such cells within the tumor usually favors tumor growth which implies the necessity of FOXP3 inhibition to improve cancer therapies." (PMID 30340426, 2018). "FOXP3+ Treg cell density (cells/mm2) was significantly increased within tumor (p = 0.002) and non-tumor normal (p = 0.021) tissues after BCG treatment." (PMID 30344922, 2018). "TGF-β produced by tumor-associated MDSCs, together with IL-10 and scarcity of arginine expression, has been shown to facilitate the differentiation and expansion of forkhead box P3 (FOXP3)+ Tregs in other tumor types." (PMID 30619286, 2018). "The expression of these genes is variable within the FOXP3+ T cells, suggesting that the transcriptional activities of these genes are dynamically regulated over time in tumor-infiltrating Treg." (PMID 30061879, 2018).
tumor (continued). "Meanwhile, it significantly reduced Treg cells CD4+CD25+Foxp3+ in the tumor microenvironment in comparison to PBS group (6.13%, 2.32%, 5%, and 12.9%) respectively." (PMID 29959375, 2018). "Previously, MDSCs have been shown to mediate CD4+ Foxp3+ Treg development in mouse tumor models in vivo." (PMID 29497426, 2018). "Our results suggest the combination of CD25, TGF-β and PD-1 effectively inhibited tumor formation and progression via depleting tumor infiltrating FoxP3+ Tregs and enhancing anti-tumor immune response on the basis of IIR." (PMID 30359281, 2018). "Further, we suppressed the expression of STAT5 by transfection of siRNA-STAT5 and detected the levels of TET2 binding to FOXP3-TDSR in CD4+ T cells from tumor tissues." (PMID 30013992, 2018). "Our study revealed the heterogeneity of FOXP3+ Treg at the single-cell level and showed that tumor-infiltrating Treg include FOXP3+ T cells with various levels of activation." (PMID 30061879, 2018). "The UltiMapper I/O T-Reg panel included the markers CD4, CD25, and FoxP3, as well as a tumor markers pan-cytokeratin (CK) for carcinomas and Sox10 for melanomas." (PMID 30400822, 2018). "The cytoplasmic, perinuclear and nuclear pattern of Foxp3 immunoexpression on tumor infiltrating cells was seen in all OSCC cases and 9 control cases." (PMID 28669079, 2018). "Recently, we described the Cumulative Suppression Index (CSI), which examines the number of CD8+ T cells in the invasive margin of tumor combined with the number of FoxP3+ or PD-L1+ cells within 30 um of CD8+ T cells." (PMID 30400835, 2018). "In this study, infiltrating FoxP3+ Tregs and TGF-β expression in tumor tissues were found to be associated with survival." (PMID 30359281, 2018). "FoxP3 staining of cells was revealed as strong nuclear reactivity, either in clustered foci in some patient sections, or scattered in the tumor stroma in other cases." (PMID 29843813, 2018). "Several previous studies have confirmed the function of CD25 blockade in depleting FoxP3+ Tregs in the tumor microenvironment, which activated FcγRs capable of inducing antibody dependent cellular cytotoxicity." (PMID 30359281, 2018). "Recently, growing evidence indicates that CD4+CD25+FOXP3+ regulatory T cells (Tregs) play a significant role in the control of tumor immunity, immune evasion and therapy resistance." (PMID 30079021, 2018). "While the mechanism has yet to be clarified, metformin also appears to alter the immune TME with an increased infiltrate of CD8+ Teff and FoxP3 Tregs at the invasive tumor margin of lymph nodes with ECE." (PMID 30364350, 2018). "Increased percentages of FOXP3+ cells with higher PD-L1 expression also suggested a tumor cell modulation of the adaptive immune response given that PD-L1/PD-1 interactions promote T-cells differentiation into regulatory cells." (PMID 29874226, 2018). "The same group found that Foxp3 expressed in tumor cells has distinct biological functions compared with that in Tregs." (PMID 30460193, 2018). "Tregs and CD4+Foxp3- cells isolated from tumor infiltrating lymphocytes (TIL) showed comparable frequencies in both strains of mice, however CD8+ T cell frequencies from TIL of IFNARfl/fl x Foxp3YFP-Cre mice were increased." (PMID 29672594, 2018). "The analyses above strongly suggested that there are two major differentiation pathways for those tumor-infiltrating T cells, which are regulated by FOXP3-driven and Tfh-like processes." (PMID 30061879, 2018). "We also examined Tregs and found that the absolute number and percentage of CD4+Foxp3+ T cells in tumours were increased, but the CD8+/Treg ratio was significantly higher after treatment with vvDD-IL-2-RG compared to other virus treatment." (PMID 30410056, 2018). "It does not appear to be due to an unequal distribution of immune suppressor cells, since FOXP3+ Tregs were scarce and even macrophages appeared to be lysing tumor cells." (PMID 29774030, 2018).